STAT3 (signal transducer and activator of transcription 3)
Diseases named in the same sentence as STAT3 in open-access papers (continued):
Sharing a sentence is not in itself a finding about the gene and the disease.
cancer (continued). "As the STAT3 pathway is mainly responsible for the regulation of cell proliferation, invasion, and angiogenesis, many reports have shown that its sustained activation promotes the metastasis of many cancers, including thymic tumors, colorectal cancers, and squamous cell carcinomas of the skin." (PMID 29794990, 2018). "In addition, inhibition of STAT3 can promote apoptosis in human cancers." (PMID 30577812, 2018). "However, the therapeutic inhibition of IL-6- and leptin-evoked signaling via Stat3 inhibitors or rapamycin in cancer therapy might still be a challenge due to systemic effects." (PMID 30224299, 2018). "Moreover, epigenetic and other mechanisms may promote upregulation of the STAT3/5 pathway, allowing cancer cells to escape drug action." (PMID 29148847, 2018). "Therefore, inhibiting CRIF1 activity could be a novel therapeutic strategy to reduce oncogenic STAT3 functions in several types of cancer." (PMID 29914167, 2018). "Thus, STAT3 appears to be a desirable drug target for cancer therapy." (PMID 30518397, 2018). "Despite a clear link between STAT3 activation and HPV-associated cancers, it is not known whether STAT3 contributes to the productive HPV life cycle." (PMID 29630659, 2018). "Among the predicted targets of miR-29b such as signal transducer and activator of transcription 3 (Stat3), cyclin-dependent kinase 6 (CDK6), lysine demethylase 2A (KDM2A) and Sirtuin-1 (SIRT-1), SIRT-1 was reported to be associated with chemoresistance in cancers." (PMID 29552311, 2018). "Therefore, inhibition of Stat3 may be a promising therapeutic strategy for the management of cancer radioresistance." (PMID 30297887, 2018). "STAT3 is a vital cytoplasmic transcription factor, and activated STAT3 (p-STAT3) is upregulated by aberrant upstream tyrosine kinases; p-STAT3 transports information to the nucleus and controls gene expression, which is essential for cancer cell growth and survival." (PMID 29560131, 2018). "Furthermore, the activations of NFκB and STAT3 could result in cancer cell proliferation, survival, invasion and metastasis by reducing the sensitivity to chemotherapy." (PMID 30479366, 2018). "Indeed, it has been reported that increased inflammatory cytokines, such as IL-6, might be involved in the enhanced phosphorylation of STAT3 in muscle tissue of cancer cachexia model." (PMID 30555329, 2018). "Furthermore, STAT3 activates miR-21 to promote cancer cell growth." (PMID 29976158, 2018). "Notably, STAT3 regulates and cooperates with NF-κΒ in additional cancer types." (PMID 29765155, 2018). "Our findings suggest that oncogenic STAT3 was particularly activated in acidic bile‐treated cells, as previously demonstrated in 45‐day acidic bile‐treated murine laryngopharyngeal mucosa with pre‐malignant lesions and deregulations of cancer‐related miRNA markers." (PMID 29516639, 2018). "Although IL6ST has been shown to activate several signaling pathways including STAT3, Janus tyrosine kinase (JAK), mitogen-activated protein kinase (MAPK), and phosphatidylinositol 3-kinase (PI3K), among them, STAT3 has been hypothesized to be a key downstream molecule in cancer." (PMID 30586414, 2018). "Therefore, identification of bioactive molecules able, on one hand, to induce apoptosis in cancer cells and, on the other, suppress STAT3 activation may potentially improve the cancer treatment outcomes." (PMID 29576846, 2018). "Cancer and inflammation are connected by the intrinsic (activated oncogenes) and extrinsic (inflammation, infections) pathways leading to the activation of the three transcription factors: NFκB, STAT3 (signal transducers and activators of transcription 3), and HIF1α (hypoxia-induced factor 1α)." (PMID 29890744, 2018). "Therefore, STAT3 is considered to be an attractive target for cancer prevention and therapy." (PMID 29686295, 2018). "Furthermore, STAT3 is involved in PD-L1 regulation in various cancer types." (PMID 29765155, 2018).
cancer (continued). "Interestingly, we noticed that both apoptosis and STAT3 abrogation induced by OP-D can be substantially reversed by antioxidants and thus ROS could play an important role in mediating the anti-cancer effects of OP-D." (PMID 30413072, 2018). "Combination of penitrem A with HER-targeting drugs, LP or GF, resulted in synergistic antiproliferative effects via STAT3 and p27 pathways, which could represent a novel strategy to improve cancer cell sensitivity to targeted regimens and reduce the emergence of resistance to these treatments." (PMID 29751615, 2018). "Besides its canonical function as transcription factor, STAT3 plays a distinct role in the mitochondria, where it supports Ras-dependent malignant transformation, promotes autophagy, and restrains ROS levels, thus increasing cancer cell survival." (PMID 29914167, 2018). "Furthermore, combining potential STAT3/5 inhibitors with approved TKIs might be beneficial in treating cancer." (PMID 29148847, 2018). "In addition, feedback activation of STAT3 may play a prominent role in mediating drug resistance to a broad spectrum of targeted cancer therapies and chemotherapies." (PMID 29588647, 2018). "Also, JAK2 phosphorylates STAT3 at Tyr705, inducing its dimerization and translocation to the nucleus where it regulates the expression of different proteins involved in cancer progression, such as cyclin D1, COX2, VEGF, and SOCS3, a negative regulator of leptin signaling." (PMID 30404206, 2018). "Therefore, in the current study, we carried out a systematic analysis combining thousands of gene expression or copy number variation analysis published online, to evaluate the expression pattern, potential functions and distinct prognostic value in cancer of STAT3." (PMID 29423040, 2018). "Hence, this study was conducted to evaluate the chemo-sensitization efficacy of SNME on adriamycin resistant cancer cells (NCI/ADR-RES) and tried at deciphering the possible involvement of SNME on STAT3 mediated chemotherapy resistance in adriamycin resistant cancer cells (NCI/ADR-RES)." (PMID 28720093, 2017). "Also, STAT3 is closely associated with VEGF or CDK2 in cancer progression." (PMID 29254203, 2017). "Therefore, targeting p-STAT3 by enhancing the activities of SHP-1 may be a strategy for inhibiting p-STAT3 in cancers." (PMID 28594363, 2017). "Moreover, several known targets of the components of the IL-6R/STAT3/miR-204 loop might be important for cancer progression." (PMID 28388577, 2017). "In summary, immunoblot assay confirmed that both canonical NF-κB and STAT3 pathways were continuously attenuated in the cancer group during MoDC differentiation, which might lead to the abnormal transcription of downstream genes and the functional deficiency of DCs." (PMID 28350008, 2017). "As STAT3 is one of the major RTKs’ downstream transcription factors, exploring novel chemotherapeutic agents able to effectively inhibit constitutive as well as inducible activation of STAT3 from multiple stimuli through biochemical modification hold greater potential to reduce cancer mortality." (PMID 28740138, 2017). "Therefore, our findings support that altholactone could represent a novel chemotherapeutic natural agent or lead scaffold against cancers that harbor constitutively active STAT3." (PMID 28178219, 2017). "Thus, targeting the STAT3 pathway using specific inhibitors may be a useful cancer treatment strategy with the potential for broad clinical application." (PMID 26061710, 2017). "However, the role and mechanism of the upregulation of total STAT3 in tumorigenesis and cancer progression remain unclear." (PMID 28413603, 2017). "Thus, inhibition of Stat3 holds great promise for future cancer treatment concepts." (PMID 28360411, 2017). "A combination of STAT3 inhibition and “oxidation therapy” may be a new strategy to address the multidrug-resistance issue due to their important roles in the survival and drug resistance of cancer cells." (PMID 28397855, 2017).
cancer (continued). "However, the inhibition of STAT3 is likely one of the main stimuli leading to autophagy induction by apigenin and indeed its activation, by regulating the release of cytokines by cancer cells as well as by immune cells, may result in autophagy inhibition." (PMID 29179721, 2017). "Therefore, the identification of modulators of STAT3 signaling could have therapeutic implications in various pathologies including cancer." (PMID 28574510, 2017). "In addition to vaccination against HCC, this strategy might also be applicable to other types of cancer that involve STAT3 over-activation." (PMID 29115974, 2017). "Furthermore, reversing the deactivated NF-κB and STAT3 signalling could be a strategy for cancer immunotherapy." (PMID 28350008, 2017). "Numerous studies reported that STAT3 signaling played important roles in several aspects of tumorigenesis via regulating cell proliferation, apoptosis, increased resistance to chemotherapeutic agents, cancer stem cell and metastasis, leading to the development and progression of cancer." (PMID 28750679, 2017). "For example, in one patient who had a local relapse followed by a liver metastasis, the liver metastasis carried a STAT3 inactivating mutation that was absent from both the primary cancer and the local relapse, despite the latter being closely related to the metastasis." (PMID 28810143, 2017). "In summary, the present study elucidated a novel role of unripe S. nigrum fruit extract in inhibiting cellular proliferation and promoting apoptosis in Adriamycin resistant cell line NCI/ADR-RES, which further suggested that STAT3 could be a potential target in modulating drug resistant cancers." (PMID 28720093, 2017). "In addition, because of their important role in cellular regulation, STAT3 PTMs might be important targets in cancer as adjuvants in chemiotherapy." (PMID 28489571, 2017). "Furthermore, it has been further demonstrated that, when macrophages were cocultured with MCF-7 cells suffering apoptosis, they secreted IL-6, activating STAT3 phosphorylation, and therefore performed a role on the activation of cancer stem cells and cancer promotion." (PMID 28970834, 2017). "For example, cancer development often involves genes controlled by STAT3 signalling, known for its role in wound healing, while the epithelial to mesenchymal transition of migratory neural crest cells has similar expression patterns to malignant cancer cell populations." (PMID 28872594, 2017). "Therefore, we examined whether STAT3 signaling was also involved in the anti-cancer activities upon SFN treatment in human GBM cells." (PMID 28054986, 2017). "Also, various prior reports indicate that pharmacological agents that can abolish STAT3 activation may have a great potential in the prevention and therapy of cancer." (PMID 28208828, 2017). "Therefore, STAT3 specific inhibitor may be useful cancer treatment and many STAT3 inhibitors are in the process of being tested in clinical trials." (PMID 28245605, 2017). "In addition to IL-6, STAT3 can be activated by EGFR in many cancer types." (PMID 29262529, 2017). "However, various types of cancer constitutively express PD-L1, either as a result of structural alterations in the regulatory 3′ region of the PD-L1 gene, or through activation of the STAT3 and AKT pathways, which are common features of cancer." (PMID 28507803, 2017). "Therefore, inhibiting STAT3 activity by targeting STAT3 directly could be a highly beneficial strategy for the successful treatment of cancer." (PMID 28636670, 2017). "STAT3 may play an important role in remodeling the extracellular matrix, exploiting inflammatory mechanisms, and evading immune surveillance to create a metastatic niche to facilitate spread of the cancer." (PMID 28030809, 2017).
cancer (continued). "Moreover, STAT3 and NF-κB are both responsible for promoting inflammation by increasing the expression of well-known proinflammatory cytokines such as TNFα and IL-6, which in turn lead to cancer initiation and progression." (PMID 28362332, 2017). "Furthermore, as a key transcription factor, STAT3 may be phosphorylated by ERK1/2 to drive biological functions in cancer cells." (PMID 26882566, 2016). "In addition, the level of acetylated STAT3 is relatively high in cancer cells." (PMID 27183223, 2016). "Therefore, interrupting STAT3 signaling can suppress cancer drug resistance, growth and metastasis." (PMID 27556503, 2016). "Therefore, inhibition of STAT3 signaling may be a viable therapeutic approach for these two cancers." (PMID 26883202, 2016). "Activation of STAT3 and its effects have been examined using virus infection models in culture, virus-infected/transformed cell lines (including those derived from patients with virus-related cancers), mouse models, and by selectively expressing viral proteins or their domains in uninfected cells." (PMID 27458446, 2016). "Therefore, it may be a potential and promising strategy to target acetylated STAT3 in cancer therapy." (PMID 27183223, 2016). "In parallel, since in different cancer cells Mcl-1 is induced by Akt and STAT-3 intracellular pathways, which are implicated in B-CLL pathogenesis, we have investigated the potential involvement of Akt and STAT-3 in the anti-leukemic activity of Met-DCA cocrystal." (PMID 26959881, 2016). "Thus, in the setting of HG, down-regulated Grim-19 could serve as a sensor and transmit the signaling of mitochondria to the nucleus through its interaction with STAT3, promoting the survival of cancer cells or proliferation of the cells such as H9C2." (PMID 27101310, 2016). "Therefore, inhibition of STAT3 may be an effective medical treatment to sensitize cancer cell to apoptotic stimuli such as radiation or anticancer drugs." (PMID 27517746, 2016). "Interestingly, we found that Rhus coriaria inhibited STAT3 phosphorylation in a concentration-dependent manner in MDA-MB-231 cells, thus suggesting that STAT3 inactivation might contribute to the anti-cancer effect of Rhus coriaria." (PMID 26888313, 2016). "However, STAT3 knockdown or overexpression of both mutated STAT3s did not have any effects on the survival and apoptosis in bulk cancer in monolayer culture." (PMID 27306323, 2016). "IL-6 and IL-8 can further activate STAT3, which has been shown to promote apoptotic resistance and contribute to poor prognosis of cancer patients Although TRAF6 is known to mediate LPA-stimulated NF-κB activation, it is not clear whether TRAF6 plays a particular role in the LPA2 receptor signaling." (PMID 27134758, 2016). "The transcription factor STAT3 promotes tumorigenesis mainly through preventing apoptosis by up-regulating the expression of apoptosis inhibitors in several primary human cancers, and blockage of constitutive STAT3 signaling results in the growth inhibition and apoptosis in cancer cells." (PMID 26861252, 2016). "The finding that persistent activation of STAT3 is dispensable for normal cells but is essential for the development and progression of tumors strongly suggests that STAT3 could be a potential therapeutic target for cancers." (PMID 26883202, 2016). "Thus, it is suggested that targeting JAK2/STAT3 proteins may represent an important therapeutic target for novel cancer therapy." (PMID 26755649, 2016). "Hence, STAT3 is widely recognized as a potential drug target for cancer therapy." (PMID 26888313, 2016). "Therefore, these anti-inflammatory and antiapoptotic properties of quercetin have a key role in the reduction of cancer by controlling the toll-like receptor-2 (TLR2) and JAK2/STAT3 pathway and causing the inhibition of STAT3 tyrosine phosphorylation within inflammatory cells." (PMID 27589790, 2016).
cancer (continued). "Besides the ability to inhibit NF-κB/STAT3, we show that GL may target cancer cell progression by the activation of ATM/ATR pathway, inducing a rapid CDC25C degradation in DU145 cells." (PMID 26683224, 2016). "Furthermore, the residual cancer cells in the resected specimens expressed IL-6, IL-6R and p-STAT3." (PMID 25761055, 2015). "Thus, Stat3 and NF-κB decreases are very important in cancer therapy." (PMID 26169986, 2015). "Although a large number of growth factors and cytokines can stimulate STAT3 activity, which could have synergistic effects on prolonging STAT3 activation, many growth factors, cytokines and other factors that induce STAT3 activity in inflammation and cancer require the IL-6 signaling pathway." (PMID 26501341, 2015). "Also, phosphorylation of the latent cytosolic transcription factor STAT3 that is aberrantly activated in many cancers, including NSCLC and is responsible for up-regulated expression of several cell cycle regulators and anti-apoptotic proteins, was significantly decreased by DACE." (PMID 25674792, 2015). "Furthermore, we observed reduced STAT3 signaling in silibinin-treated cancer cells." (PMID 26510913, 2015). "Moreover, it may regulate various molecular targets including EGF, PDGF, VEGF, NF-kB, and STAT3 in cancers." (PMID 26490686, 2015). "However, recent reports indicate that autocrine induction of IDO by IL-6 is STAT3-dependent in some cancer cells or in myeloid suppressor cells, suggesting that cytokines may induce IDO expression through different STAT pathways." (PMID 26657115, 2015). "However, further studies should be conducted regarding STAT3 silencing for cancer therapy." (PMID 26631279, 2015). "STAT3 is a component of the signal transducers and activators of the transcription (STATs) family, which acts as an important transcription factor, and plays a role in normal development and cancer progression by regulating cell survival, proliferation, and apoptosis." (PMID 25963978, 2015). "Interestingly, STAT3 promotes cancer invasion also by modulating EMT." (PMID 28031890, 2015). "Therefore, targeting STAT3 is a valid strategy for cancer therapy." (PMID 25915156, 2015). "In conclusion, the present study provides evidence that the dysregulation of ROR1 results from miR-27b-3p downregulation in GC and may promote cancer progression, and the c-Src/STAT3 signaling pathway was involved in miR-27b-3p-ROR1-mediated cell proliferation regulation." (PMID 26576539, 2015). "Typically, activation of STAT3 occurs by cytokine mediated JAK phosphorylation of tyrosine 705, however, a second phosphorylation site exists at serine 727 and is phosphorylated through MEK and its transient or constitutive activation in cancer cells has been associated with survival." (PMID 25953027, 2015). "We have examined the hypothesis that, similar to bacterial infections, chronic HPV infection may also be able to collaborate with Stat3 signaling, triggering an inflammatory response that facilitates the formation of a microenvironment favorable for carcinogenesis and/or cancer progression of CRC." (PMID 25706309, 2015). "Furthermore, upregulation of STAT3 in cancers can contribute to cell growth." (PMID 26389681, 2015). "In order to examine whether STAT3 signaling is also activated in the residual cancer cells after chemoradiotherapy, the expression of IL-6R and p-STAT3 was further examined immunohistochemically in the 12 patients of the high expression group with poor response to chemoradiotherapy." (PMID 25761055, 2015). "Furthermore, a therapeutic strategy combining BH3 mimetics with STAT3 inhibitors could have potential implications in cancers where one and/or both signaling networks are deregulated." (PMID 26430964, 2015).